RN7SL379P (RNA, 7SL, cytoplasmic 379, pseudogene)
Gene: Miscellaneous RNA gene on chromosome X (96,023,360 to 96,023,652, forward strand). Ensembl gene ENSG00000242998.
Homologues: Orthologues: chimpanzee Metazoa_SRP (99% identical), macaque Metazoa_SRP (93% identical). Paralogues in human: RN7SL1 (78% identical), RN7SL2 (77% identical), RN7SL88P (77% identical), RN7SL3 (77% identical), RN7SL296P (76% identical), RN7SL804P (76% identical), Metazoa_SRP (76% identical), RN7SL322P (76% identical), RN7SL408P (76% identical), RN7SL126P (75% identical), RN7SL567P (75% identical), Metazoa_SRP (75% identical), and 703 more.